FLT1 (fms related receptor tyrosine kinase 1)
Diseases named in the same sentence as FLT1 in open-access papers (continued):
Sharing a sentence is not in itself a finding about the gene and the disease.
abortion (1 paper, 2023). the ending of pregnancy by removing a fetus or embryo before it can survive outside the uterus. "Thus, we hypothesized that the reduction in FLT-1+ dMφs might be associated with the imbalance of M1/M2 in spontaneous abortion." (PMID 37033974, 2023). "Most importantly, we discovered that the level of PlGF secreted by DSCs and the level of FLT-1 (the only known signaling receptor for PlGF) in dMφs were significantly lower in spontaneous abortion than those in normal pregnancy." (PMID 37033974, 2023). "The mRNA level of FLT1 in dMφs from patients with spontaneous abortion was also lower than that of normal pregnancy." (PMID 37033974, 2023). "The downregulated expression of PlGF/ FLT-1 may result in spontaneous abortion by inducing the M1-like deviation of macrophages in human early decidua." (PMID 37033974, 2023). "Moreover, the CBA/J×DBA/2 abortion-prone mice displayed a lower FLT-1 expression in uterine macrophages than did CBA/J×BALB/c control pregnant mice." (PMID 37033974, 2023). "Interestingly, with the help of FCM, FLT-1+ macrophages were found in the early decidua and a prominent reduction of FLT-1+ dMφs was observed in patients with spontaneous abortion when compared with normal pregnancy (16.65 ± 1.06% vs. 44.83 ± 1.47%)." (PMID 37033974, 2023).
Acidosis (1 paper, 2022). Abnormal acid accumulation or depletion of base. "While angiopoietin 2 (Angpt-2) and P-selectin were associated with TFF3, I-FABP was correlated with soluble Fms-related receptor tyrosine kinase 1 (sFlt-1) as well as soluble vascular cell adhesion molecule 1 (sVCAM-1) in children with acidosis." (PMID 36069443, 2022).
adenosquamous carcinoma (1 paper, 2014). A carcinoma composed of malignant glandular cells and malignant squamous cells. "We detected MAML2 rearrangement using fluorescence in situ hybridization (FISH) in tissue samples from 42 cases of PMEC and 40 of adenosquamous carcinoma (ASC), and the expression of potential downstream targets of MECT1-MAML2, including HES1, FLT1 and NR4A2 with immunohistochemistry (IHC)." (PMID 24714697, 2014).
Ascites (1 paper, 2013). Accumulation of fluid in the peritoneal cavity (between the layers of the peritoneum that lines the abdomen). "The Flt-1 expression level of the 18 cases with ascites <1000 ml was 45.2%, evidently lower than that of the patients with ascites ≥1000 ml (78.3%); the difference was significant (P=0.02)." (PMID 23946799, 2013).
bone sarcoma (1 paper, 2023). A sarcoma that arises from the bone.
cardiomyopathy (1 paper, 2025). A disease of the heart muscle or myocardium proper. "This study aimed to explore the protective effect of sitagliptin on cardiomyopathy in the type I DM murine model and if its impact is associated with changes in the expression of mTOR, VEGF, and FLT-1." (PMID 40867548, 2025).
colon adenocarcinoma (1 paper, 2023). "We observed the highest correlation coefficients for colon adenocarcinoma (COAD), with R = 0.62 for FAP and FLT1 and R = 0.55 for FAP and KDR." (PMID 36672341, 2023).
dystrophinopathy (1 paper, 2019). "This also led to an improved mdx-associate muscle pathology, confirming that postnatal deletion of Flt1 is able to rescue the dystrophinopathy related muscle pathology." (PMID 31877123, 2019).
fracture (1 paper, 2025). "In a murine femoral fracture model, inhibition of VEGF signaling by Fms-related receptor tyrosine kinase 1 (Flt-1), delayed cartilage turnover, disrupted conversion of soft cartilaginous callus to a hard bony callus, and impaired fracture healing." (PMID 40025573, 2025).
giant cell tumor of bone (1 paper, 2025). "In giant cell tumor of bone (GCTB), genes associated with bone vascular formation (OPG) and neoangiogenesis (FLT1) exhibit opposite expression patterns, with OPG significantly downregulated and FLT1 upregulated." (PMID 41450931, 2025).
HCMV infection (1 paper, 2015). "Strikingly, s-flt-1 levels are increased in the amniotic fluid of patients with congenital HCMV infection, and could thereby represent a negative modulation of excessive PLGF signal due to increased levels of 15-HETE resulting from HCMV infection." (PMID 26171612, 2015).
hydatidiform mole (1 paper, 2019). A gestational trophoblastic disorder characterized by marked enlargement of the chorionic villi, hyperplasia of the villous trophoblastic cells and hydropic changes. "Double staining of LIGHT and Flt-1/sFlt-1 revealed that LIGHT and sFlt-1 are co-localized in trophoblast cells of hydatidiform mole." (PMID 31300808, 2019).
invasive carcinoma (1 paper, 2005). A carcinoma that is not confined to the epithelium, and has spread to the surrounding stroma. "In contrast, Flt-1 was significantly higher expressed in the group of DCIS with an adjacent invasive carcinoma irrespective of nuclear grading." (PMID 15841074, 2005).
lobular carcinoma (1 paper, 1999). "Only a single tumour, a lobular carcinoma, failed to express Flt-1 on either cell type." (PMID 10360672, 1999).
motor neuron degeneration (1 paper, 2018). "Flt1 has been described to have a role in motor neuron degeneration." (PMID 29906661, 2018).
muscular dystrophy (1 paper, 2019). Muscular dystrophy (MD) refers to a group of more than 30 genetic diseases characterized by progressive weakness and degeneration of the skeletal muscles that control movement. "As postnatal gene deletion and pharmacological inhibition of FLT1 decreased the muscular dystrophy-associated pathology in the mdx mice, we next sought to examine whether it could do this in a more translational manner using biologics to block FLT1." (PMID 31877123, 2019).
nematode infection (1 paper, 2023). "To determine whether the nematode infection-regulated Vegfa and Flt1 mRNA expression are IL-4 dependent, we investigated their expression levels in thioglycolate and nematode-elicited peritoneal macrophages derived from Il4ra-/-mice." (PMID 37215144, 2023). "Additionally, the nematode infection-induced Flt1 mRNA level also showed a partial IL4Rα dependency." (PMID 37215144, 2023).
ovarian hyperstimulation syndrome (1 paper, 2017). A complication of ovulation induction in infertility treatment. "VEGF levels are also elevated while its circulating receptor Flt-1 levels are decreased in the follicular fluid of women with PCOS undergoing controlled ovarian hyperstimulation compared with controls, which may explain their increased risk of ovarian hyperstimulation syndrome." (PMID 28350328, 2017).
papillary thyroid carcinomas (1 paper, 2022). "They showed that coexpression of VEGF and two high-affinity tyrosine kinase receptors in VEGF signaling, namely, VEGFR-1/Flt-1 and VEGFR-2/KDR, were expressed in papillary thyroid carcinomas (PTCs), including follicular variants." (PMID 35923625, 2022).
parasite (1 paper, 2023). "Nevertheless, the determination of the functional consequences of this modified macrophage-expressed Vegfa and Flt1 pattern in parasite infections requires further experimental work." (PMID 37215144, 2023). "Overall, these results indicate that Flt1 was induced in the alternatively polarized macrophages during different parasite infections, while the in vivo regulation of the Vegfa expression depends on the parasite infection models." (PMID 37215144, 2023). "Next, we investigated the Vegfa and Flt1 mRNA expression levels in the hypothalamic monocytes, macrophages and microglial cells derived from naïve and Trypanosoma brucei-infected mice 45 days after the parasite infection." (PMID 37215144, 2023). "Finally, the in vivo parasite infection generally leads to elevated Flt1 expression in the alternatively polarized murine macrophages derived from the peritoneal cavity and the brain, while the regulation of Vegfa mRNA level depends on the site and/or species of parasite infection." (PMID 37215144, 2023).
parathyroid cancer (1 paper, 2021). "LINC00959 and lnc-FLT3–2:2 may participate in parathyroid cancer through downregulating FLT1." (PMID 33910638, 2021).
Parkinson disease (1 paper, 2023). A progressive degenerative disorder of the central nervous system characterized by loss of dopamine producing neurons in the substantia nigra and the presence of Lewy bodies in the substantia nigra and locus coeruleus. "This study reports for the first time the potential mechanisms and diagnostic value of FLT1, ATP6V0E1, ATP6V0E2, and H2BC12 in regulating the immune microenvironment in Parkinson's disease." (PMID 37908486, 2023). "This study demonstrates the significant value of constructing a diagnostic model using FLT1, ATP6V0E1, ATP6V0E2, and H2BC12, and their importance in the diagnosis of Parkinson's disease." (PMID 37908486, 2023).
polyp (1 paper, 2024). A usually exophytic mass attached to the underlying tissue by a broad base or a thin stalk. "Specifically, compared with normal tissues, monocytes, pDCs and epithelial subsets had increased expression levels of VEGFA and/or VEGFB, while endothelial cells had increased expression levels of VEGF receptors FLT1 and KDR in three polyp subtypes." (PMID 38264936, 2024).
Premature ovarian insufficiency (1 paper, 2025). Amenorrhea due to loss of ovarian function before the age of 40. "Studies have shown that tsRNA-3043a can enhance the apoptosis and senescence of ovarian granulosa cells by targeting FLT1, thereby promoting the development of premature ovarian insufficiency." (PMID 40809958, 2025). "For instance, tsRNA-3043a promotes apoptosis in ovarian granulosa cells by targeting FLT1, thereby exacerbating premature ovarian insufficiency, In contrast, tsRNA-04002 inhibits apoptosis in nucleus pulposus cells by suppressing PRKCA, thus delaying intervertebral disc degeneration." (PMID 40809958, 2025).
pulmonary sarcoidosis (1 paper, 2009). Sarcoidosis affecting the lung parenchyma. "A statistically significant decrease has been detected in Flt-1 protein expression in IPF in comparison with pulmonary sarcoidosis (mean ± SD, 18.8 ± 6.5 versus 3.0 ± 1.4, P = .036, resp)." (PMID 20169144, 2009). "We hypothesized that the levels of VEGF and receptor Flt-1 would be higher in bronchoalveolar lavage fluid (BALF) from patients with IPF than in patients with pulmonary sarcoidosis." (PMID 20169144, 2009). "Moreover, a statistically significant decrease has been found in Flt-1 protein levels in pulmonary sarcoidosis in comparison with IPF (P = .03)." (PMID 20169144, 2009). "We estimated the levels of vascular endothelial growth factor (VEGF) and its high-affinity receptor, Flt-1 (fms-like tyrosine kinase 1), in bronchoalveolar lavage fluid (BALF) of patients with IPF and pulmonary sarcoidosis." (PMID 20169144, 2009).
pyometra (1 paper, 2020). "In fact, the endometrial neovascularization in the pyometra group is confirmed by higher immunostaining of VEGF-A and its receptors (FLT-1 and KDR), and angiogenesis is associated with simultaneous increased uterine expression of the COX-2 inflammatory marker." (PMID 32784584, 2020).
renal pelvis carcinoma (1 paper, 2024). A carcinoma arising in the renal pelvis. "Additionally, the FLT1-targeted drug ICRUCUMAB was in phase II trials for bladder, urethra, ureter, or renal pelvis carcinoma." (PMID 38576019, 2024).
respiratory failure (1 paper, 2025). The significant impairment of gas exchange within the lungs resulting in hypoxia, hypercarbia, or both, to the extent that organ tissue perfusion is severely compromised. "One SNP (rs4957796) in FER was associated with 28-day survival (p = 3.4 × 10−9) and mortality (p = 5.6 × 10−8), and rs9508032 in FLT1 was associated with respiratory failure (p = 5.2 × 10−8)." (PMID 40168842, 2025). "Two SNPs emerged from the GWASs: rs4957796 in FER was associated with survival (Cox regression: p = 3.4 × 10−9), and rs9508032 in FLT1 was associated with respiratory failure (logistic regression: p = 5.2 × 10−8)." (PMID 40168842, 2025). "We found significant associations between certain genetic loci and critical outcomes, such as rs4957796 in FER and rs2569190 in CD14 associated with mortality, and rs9508032 in FLT1 with respiratory failure." (PMID 40168842, 2025). "Our systematic review revealed significant associations between the genes CD14, FER, and mortality/survival, as well as FLT1 and respiratory failure among critically ill patients." (PMID 40168842, 2025).
Splenomegaly (1 paper, 2014). Abnormal increased size of the spleen. "Female Tet-mev-1 mice exhibit thrombocytosis and splenomegaly in both non-pregnant and pregnant mice as well as placental angiodysplasia with reduced Flt-1 protein leading to hypoxic conditions, which could contribute to placental inflammation and fetal abnormal angiogenesis." (PMID 24936442, 2014).
ulcerative colitis (1 paper, 2016). An inflammatory bowel disease involving the mucosal surface of the large intestine and rectum. "Five (42%) of the associated genes with these CpG sites have been linked to either ulcerative colitis (FLT1 and ELTD1) or CRC (PCDHG4A, GJD2, and TP53I11)." (PMID 27006956, 2016).
Venous malformation (1 paper, 2022). A vascular malformation resulting from a developmental error of venous tissue composed of dysmorphic channels lined by flattened endothelium and exhibiting slow turnover. "It has a high mutational component, with overexpression of genes associated with angiogenesis, such as TIE1, VEGFR2, SNF-1, TEK (kinase associated with venous malformations), and FLT1." (PMID 36555675, 2022).
tumor (912 papers, 1999 to 2026). "Vascular Endothelial Growth Factor Receptor 1 (VEGFR-1 or Flt-1), a tyrosine kinase receptor, holds significant relevance in tumor-associated angiogenesis and mediates mitogenic functions." (PMID 40009629, 2025). "The difference in tumor growth only becomes pronounced after PARPi treatment, presumably when Flt1-deficient tumor cells are eliminated, and Flt1-proficient cells persist." (PMID 38956205, 2024). "This study revealed that Nestin and FLT1 expressions in RCC were significantly associated with aggressive tumor parameters." (PMID 39687450, 2024). "Further validation of the FFL (PDGF/FLT1/SHC1) as predictive factor for the survival of the PIK3CA-mutated luminal-A tumor patients is necessary." (PMID 28392480, 2017). "In summary, taking a systems approach based on the cancer hallmark network framework, we found that the FFL (PDGF/FLT1/SHC1) is significantly enriched in the PIK3CA-mutated luminal-A tumor patients." (PMID 28392480, 2017). "Nestin and FLT1 expressions in RCC may be associated with aggressive tumor features and short patients’ overall survival." (PMID 39687450, 2024). "FLT1 positivity was also associated with larger tumor size (P=0.007)." (PMID 39687450, 2024). "Since PGF expression increases locally in the tumor milieu upon PARPi treatment, it is possible that a minor subpopulation of Brca1- and Bard1-deficient tumor cells that express the PGF receptor FLT1 prior to PARPi treatment becomes enriched in the PARPi-resistant tumors." (PMID 38956205, 2024). "Moreover, in lung, pancreatic, and breast cancer models, Flt1 signaling in tumor-associated macrophage (TAM) has been shown to be necessary to support tumor angiogenesis." (PMID 35011579, 2021). "For expression of genes involved in vascular morphogenesis and maturation, it was reported that low VEGFB and high FLT1 in primary tumours and high ACVRL1 levels in liver metastases were associated with enhanced OS of CRC patients with liver metastases treated with bevacizumab plus chemotherapy." (PMID 29535825, 2018). "More investigation of the molecular mechanisms of the FFL (PDGF/FLT1/SHC1) in the PIK3CA-mutated luminal-A tumor patients could lead to better predictions and more personalized treatment." (PMID 28392480, 2017). "Finally, mechanical explorations suggest that Radiomics models may be associated with tumor angiogenesis-related pathways, of which FLT1 was highlighted." (PMID 41023751, 2025). "Moreover, statistically significant associations were found between both positive FLT1 expression and high expression level and high tumor grade (P=0.032 and 0.002), wide tumor extent (P=0.003 and 0.002), advanced tumor stage (P=0.032 and 0.001) and high MVD (P=0.01 and 0.007)." (PMID 39687450, 2024). "Meanwhile, the analysis of NGS detected two tumor-specific mutated genes: MYC (gene amplification, CN: 59.5) and FLT1 (missense mutation, c.1061G>A (p.R354Q), abundance: 2.1%)." (PMID 42094195, 2026). "Significant research has shown that bone marrow cells expressing FLT1 (VEGFR1) travel to these distant sites in response to molecules released by the original tumor." (PMID 41596524, 2026). "In the high-risk state, the expression levels of VEGFA were significantly increased in Macrophages, Mast cells, Monocytes and tumor cells; FLT1 and KDR were significantly increased in Endothelial; and PGF was significantly increased in Mesangial." (PMID 40563096, 2025). "• Radiomics models have value in revealing tumor angiogenesis, blood supply levels, and FLT1 expression." (PMID 41023751, 2025). "These ligands, especially VEGF-A, bind to receptors such as VEGFR-1 (Flt-1), VEGFR-2 (KDR/Flk-1), and VEGFR-3, along with the coreceptor neuropilins, to induce normal and tumor-associated angiogenesis." (PMID 38498275, 2024). "We first engineered lentiviruses to deplete Flt1 expression (“Flt1i”) in the tumor cells by CRISPR-mediated gene repression (CRISPRi) using two independent guide RNAs (“gRNA1” or “gRNA2”) (EV3E,F)." (PMID 38956205, 2024).